GDF15 (growth differentiation factor 15)
Diseases named in the same sentence as GDF15 in open-access papers (continued):
Sharing a sentence is not in itself a finding about the gene and the disease.
cancer (continued). "Whilst sorafenib led to a threefold induction of GDF15 on average, sunitinib did not lead to notable GDF15 regulation in any of the NCI-60 cancer cell lines." (PMID 37495707, 2023). "Inhibition of GDF15 activity with antibodies targeting either GDF15 or its receptor GFRAL was found to reverse chemotherapy-induced anorexia and emesis and cancer cachexia in mice and nonhuman primates." (PMID 34831213, 2021). "A differential expression pattern was found in cancer tissues representing several forms of cancer, within CRC ranging from negative tumours to tumours with strong GDF15 expression." (PMID 21468045, 2011). "If confirmed, this may be a possible explanation for the contradictory growth-promoting effects evidenced in several cancer types, but not in RCC, in which GFRAL presence is decreased and in which GDF-15 rather inhibits progression." (PMID 39000420, 2024). "Further, unlike many cancers, TRAMP PCa do not express GDF15." (PMID 32502202, 2020). "Furthermore, in the general population, GDF-15 was the only biomarker additionally predictive for non-CVD and cancer mortality." (PMID 32993054, 2020). "In addition, GDF15 or IMQ treatment did not activate the JNK and P38 MAPK signaling pathways in GSCLCs, though these signaling pathways are also suggested to be involved in cancer stemness." (PMID 33431816, 2021). "To confirm whether this negative correlation between GDF15 and GDF11 is the result of target-specific inhibition of BRD4 or due to a non-specific effect of the drug on other targets, we looked up literature for gene expression profiling after BRD4 gene knockdown in cancer cell lines." (PMID 37495707, 2023).
tumor (441 papers, 2005 to 2026). "Stepwise multivariate logistic regression analysis estimated that tumor location (P = 0.001) and plasma GDF15 concentration (P = 0.020) were risk factors for infectious complications." (PMID 41016991, 2026). "In basic research, circulating GDF15 levels have been correlated with the loss of food intake, tumor size, and skeletal muscle atrophy in tumor-bearing animals." (PMID 41016991, 2026). "Treatment with a GDF15-neutralizing antibody or silencing GDF15 from tumor cells prevents adipose/muscle loss, strength decline, and weight reduction, identifying tumors cells as the GDF15 source." (PMID 41617691, 2026). "GDF15 plays a unique role in connecting metabolic stress and susceptibility to ferroptosis with tumor behavior, especially in RCC." (PMID 41009692, 2025). "Elevated GDF15 levels also reduce anti-tumor immunity by modulating NF-κB signaling and tumor-associated macrophage (TAM) activity." (PMID 40868185, 2025). "After adjusting for confounders, including patient demographics, tumor-specific variables, and laboratory values, the strong relationship between GDF-15 and all-cause mortality persisted (adjusted HR: 1.37; 95% CI: 1.25-1.50)." (PMID 39967200, 2025). "Higher IL‐6 and GDF‐15 levels were also associated with higher tumour stages (both p < 0.01), positive lymph nodes (p = 0.02 and p < 0.01) and unfavourable surgical margins (both p < 0.01)." (PMID 41380167, 2025). "Although high circulating levels of GDF15 are associated with poor prognosis, the mechanistic underpinnings of its involvement in tumor biology and cachexia require further elucidation." (PMID 40868185, 2025). "We also found high GDF‐15 levels to be associated with advanced tumour stages and positive surgical margins." (PMID 41380167, 2025). "GDF‐15 has been linked to tumour progression, immune modulation and systemic metabolic alterations that contribute to muscle wasting." (PMID 41380167, 2025). "Elevated serum concentrations of GDF15 have been associated with various malignancies, indicating its potential utility as a diagnostic biomarker for neoplastic diseases." (PMID 40725563, 2025). "Unfavourable pathologic characteristics including higher tumour stage, positive lymph nodes and positive surgical margins were all associated with higher levels of GDF‐15 (all p < 0.01)." (PMID 41380167, 2025). "GDF15 acts as a stress-response cytokine and has been implicated in tumor-induced metabolic dysregulation, particularly anorexia and cachexia." (PMID 40725563, 2025). "Next, we thoroughly investigated off‐target effects by identifying sites within the tumor tissue that pose the highest risk for off‐target genomic sequence alterations, particularly focusing on GDF15 sequence sites." (PMID 38704691, 2024). "In a microarray study of 150 human carcinomas from 10 anatomical sites, GDF15 showed the highest level of tumor-associated expression of any protein." (PMID 38711789, 2024). "The C18ORF8 gene encodes the protein MIC-1/GDF15 (Cytokine-1 macrophage inhibitor) which has frequently been reported to be present in this type of neoplasm." (PMID 39058128, 2024). "High levels of GDF15 in the tumor or in the cerebrospinal fluid are associated with a poor prognosis for GBM patients." (PMID 38201456, 2023). "Next-generation sequencing of tumor tissue (n = 40) as well as TCGA database mining confirmed that GDF-15 mRNA levels are unrelated to mutational load (p = 0.5 for both test cohort and TCGA-based analysis)." (PMID 37474523, 2023). "As a marker for the failure of anti-PD-1 therapy, GDF-15 is hence independent from PD-L1 or tumor mutational burden." (PMID 37474523, 2023). "High‐tumor GDF15 was further linked with reduced overall survival in head and neck, kidney and liver cancers." (PMID 36642986, 2023). "In regard to its obvious pleiotropic and sometimes opposite effects, GDF-15 is suggested as a biomarker of tumor severity or as a diagnostic/therapeutic target against metastasis." (PMID 36230513, 2022).
tumor (continued). "Due to the positive correlation between the level of GDF-15 and the advanced tumor stage, GDF-15 has been reported as a potential diagnostic and prognostic biomarker for PCa13." (PMID 36261691, 2022). "Of note, a few targeting GDF15 inhibitors are available and further explorations are still needed to address the underlying mechanisms of GDF15 dependent on tumor invasion." (PMID 35327584, 2022). "Another example is growth differentiation factor 15 (GDF15), which mediates tumor-induced body mass loss in xenograft mouse tumor models." (PMID 35319749, 2022). "Intriguingly, it has recently been reported that a GDF15-neutralizing antibody reverses anorexia and body weight loss and promotes survival in mouse tumor models." (PMID 35626166, 2022). "GDF15 has been suggested as a tumor-associated clinical biomarker suitable for liquid biopsy detection." (PMID 34359681, 2021). "The scientists agree that the overexpression of GDF15 is strongly associated with the degree of tumor differentiation, which is also confirmed by our results." (PMID 34149933, 2021). "In this study, we demonstrated that GDF15 expression inversely correlated with tumor-associated macrophage." (PMID 34948431, 2021). "For instance, secreted GDF15 of fibroblasts was identified to be involved in fostering a senescence-associated tumor microenvironment that promotes proliferation and invasion of COAD cells." (PMID 34948431, 2021). "In the intestine, senescent fibroblasts secrete growth differentiation factor 15 (GDF15), a senescence-associated factor, which stimulates dysregulated epithelial cell proliferation, migration, and, ultimately, tumor formation." (PMID 34376677, 2021). "GDF15 is a secreted protein induced by the tumor suppressor protein, which is implicated as a growth inhibitory molecule in tumor cells." (PMID 34445593, 2021). "During PDAC development, this induces in fibroblasts an increased expression and secretion of growth differentiation factor 15 (GDF15), which is implicated in the mechanisms of tumor cell migration and invasion." (PMID 34503252, 2021). "Growth differentiation factor 15 (GDF15), a member of the transforming growth factor β family, is associated with tumor progression, metastasis, and cell apoptosis." (PMID 33431816, 2021). "The clinical and tumoral characteristics of APC patients with high serum GDF-15 levels are expected to provide useful information for elucidating the causes of clinical symptoms triggered by stress responses in the tumor microenvironment." (PMID 34638326, 2021). "Beyond its cachectic effect, GDF15 has been also implicated in tumor cell apoptosis and the development of metastasis." (PMID 33442410, 2021). "In murine models of tumours, mice overexpressing GDF15 showed weight loss, and the degree of weight loss was proportional to the elevation of serum levels of GDF15." (PMID 33178828, 2020). "In esophageal cancer, elevated GDF-15 was positively associated with tumor invasion (p = 0.030), lymph node metastasis (P = 0.007), and shorter relapse-free (p = 0.050) and tumor-specific survival (p = 0.005)." (PMID 32508832, 2020). "Tumor-associated macrophages infiltrate tumors and produce inflammatory cytokines and chemokines, including growth differentiation factor 15 (GDF15), a member of the human transforming growth factor-β (TGF-β) superfamily." (PMID 32854281, 2020). "Expression of CENPF, AGR2, and GDF15 was found to be enriched in mpMRI-visible tumours and was associated with reduced time to biochemical recurrence in an independent dataset, suggesting a potential link between mpMRI visibility and prognostic outcome." (PMID 33000006, 2020). "Such a protective role is supported by studies indicating that tumor tissue localized GDF15 staining is associated with a better outcome in patients with early stage PCa." (PMID 32502202, 2020).
tumor (continued). "During the early stage of pancreatic tumorigenesis, GDF-15 can restrain tumor-associated macrophage activity by inhibiting NF-κB signaling, thereby evading macrophage immune surveillance." (PMID 33201838, 2020). "By doing so, we identified WNT5a, TGFBI, and SERPINE1, all recently associated with the GBM mesenchymal subtype and tumor invasion, as well as GDF-15, also known to be linked to GBM progression and poor prognosis." (PMID 31453379, 2019). "Instead, we found that senescence‐associated GDF15 mediated tumor‐promoting effects through the MAPK and PI3K pathways." (PMID 31389184, 2019). "Exogenous GDF15 is sufficient to cause weight loss in mice, and GDF15-neutralizing antibodies prevent tumor-associated weight loss." (PMID 31432710, 2019). "Related to the progression of tumor formation, resistance to GDF-15 is associated with changes in the pathways activated by this hormone." (PMID 29467963, 2018). "As a result, this cytokine can cause the migration of certain tumor lines sensitive to GDF-15 in the GBM tumor." (PMID 29467963, 2018). "GDF15 expression was significantly associated with high tumor grade, and ER-negative or HER2-positive status." (PMID 29212236, 2017). "We examined potential associations between GDF15 IHC staining and available clinical data, which included age, tumor size, tumor grade, disease involving >3 lymph nodes, ER and HER2 positivity, and overall survival." (PMID 29212236, 2017). "Expression of the inflammatory cytokine growth differentiation factor 15 (GDF15) is significantly elevated in many tumor types in association with epithelial mesenchymal transition (EMT), drug resistance, and progressive disease." (PMID 29212236, 2017). "Gdf15fl/flLyz2Cre mice illustrated that GDF15 deficiency in macrophages could accelerate tumor progression by suppressing the infiltration of CD8+ T cells." (PMID 41824793, 2026). "Bioluminescence imaging confirmed a lower tumor burden in mice injected with GDF15-deficient CAFs." (PMID 41035818, 2025). "High GDF15 serum levels were also associated with poor prognosis, and it has been hypothesized that it might impair durable tumor control in patients treated with anti-CTLA-4 and be predictive of failure to ICIs." (PMID 40868185, 2025). "Additionally, elevated serum levels of GDF‐15 are associated with unfavourable clinicopathologic tumour traits." (PMID 41380167, 2025). "Therefore, integrating IL‐6 and GDF‐15 inhibitors into therapeutic regimens warrants further investigation to disrupt the deleterious cycle of inflammation, muscle loss and tumour progression." (PMID 41380167, 2025). "GDF15 expression levels were positively associated with tumor stage progression." (PMID 38230211, 2024). "Additionally, while our past research has linked tumor GDF-15 expression to nivolumab response in NSCLC, the findings of the current trial emphasize the clinical importance of serum GDF-15 as a dynamic biomarker reflecting individual patient characteristics." (PMID 39766045, 2024). "Moreover, the risk signature and risk hub genes RAB42, SH2D4A, and GDF15 were highly positively correlated with the increase of these immunosuppressive tumor infiltrating cells." (PMID 37698534, 2023). "This suggests that increased levels of GDF-15 may be linked to elevated tumor exosome production, leading to proteolysis and lipolysis in cancer patients." (PMID 37755304, 2023). "Notably, GDF15 expression can also be induced following IR, hypoxia, or by tumor-associated macrophages." (PMID 38201456, 2023). "Whole exome and RNA sequencing data were analysed to investigate whether increased circulating GDF15 was associated with genomic alterations and/or increased gene expression in the primary tumour." (PMID 37045997, 2023). "However, GDF15 copy number gains in relapsed tumour tissue, observed in 8 patients, were associated with higher circulating GDF15 levels compared to tumours with copy number losses (p=0.045)." (PMID 37045997, 2023).
tumor (continued). "In PCa, increased concentrations of GDF-15 are associated with tumor progression." (PMID 36261691, 2022). "Nevertheless, we can reveal the association of tumor growth and angiogenesis with GDF15 alone." (PMID 35280749, 2022). "The extra centrosome-associated secretory pathway (ECASP) has been considered to contribute to significant changes by inducing the release of a variety of pro-invasive factors (IL-8 and growth differentiation factor 15 (GDF-15)) that are associated with tumorigenesis and tumour metastasis." (PMID 33663596, 2021). "Furthermore, GDF-15 overexpressed in reactive astrocytes caused an enhanced proliferation of GBM cells in vitro while GDF-15 deficient cells exhibit decreased in vivo tumor growth." (PMID 34084145, 2021). "Moreover, men in whom the differential GDF‐15 expression was highest between tumor and normal adjacent glands had the lowest risk of biochemical recurrence." (PMID 33784024, 2021). "This study identified tumor-driven GDF-15 as a potential cause of cachexia symptoms in APC." (PMID 34638326, 2021). "Additionally, some authors have reported that the high serum levels of GDF15 in GC patients are associated with tumor invasion and lymph node metastasis." (PMID 34149933, 2021). "This phenomenon of weight loss in murine models of tumours could be reversed by the utilization of monoclonal antibodies to GDF15 and reproduced by the utilization of recombinant GDF15." (PMID 33178828, 2020). "GDF‐15 is an established cardiovascular risk marker but is equally implicated in tumour biology." (PMID 31463975, 2019). "Both tumor-suppressing and tumor-promoting functions of GDF15 in the prostate have been implicated." (PMID 31539407, 2019). "Conversely, loss of GDF15 led to stimulation of tumor growth." (PMID 30542297, 2018). "Notably, in experimental animals, weight loss has been reversed by neutralisation of tumour-produced Gdf15 with a monoclonal antibody, encouraging further research to provide a new effective therapy to patients suffering from cardiac cachexia." (PMID 27298830, 2016). "This was associated with higher GDF15 plasma levels in the A2780cis tumor-bearing mice." (PMID 25490861, 2015). "Finally, we investigated the potential causes of enhanced tumor growth but increased response to carboplatin treatment seen in A2780cis following GDF15 silencing." (PMID 25490861, 2015). "GDF15 has been implicated both as a promoter and inhibitor of tumour growth." (PMID 21468045, 2011). "Thus, it is possible that increased GDF15 expression reflects an aggressive tumor phenotype associated with systemic catabolic effects, which could partly explain the discrepancy between the lower TNM stage and poor prognosis in our cohort." (PMID 40725563, 2025). "Moreover, we found that GDF-15 expression was positively associated with tumor size and grade." (PMID 33201838, 2020). "Furthermore, several studies demonstrated that testosterone could directly regulate the expression of GDF-15 in some tumor cells, indicating a potential association between sex hormones and GDF-15." (PMID 30819257, 2019). "Stemness-associated genes such as GDF15, ALDH1L1, GPC3, AFP, EPCAM, CD44, and CD24 were predominantly expressed in tumor cells, with varying levels across other cell types including CAFs, TECs, and TAMs." (PMID 41493679, 2026). "In healthy individuals, circulating GDF15 levels range from 200 to 1200 pg/mL, but can increase by 10- to 100-fold under conditions such as aging, pregnancy, injury, inflammation, and neoplasia." (PMID 40677718, 2025). "Tumor-derived GDF15 has been shown to attenuate the cytotoxicity of macrophages, thereby hindering macrophage-mediated tumor surveillance during tumorigenesis." (PMID 40144214, 2025).